SIRT1 (sirtuin 1)
Diseases named in the same sentence as SIRT1 in open-access papers (continued):
Sharing a sentence is not in itself a finding about the gene and the disease.
depression (continued). "Resveratrol was able to reduce the depression and anxiety of the mice by attenuating activation of microglia and the NF-kB and NLRP3 in the hippocampus by increasing Sirt1 levels." (PMID 33292508, 2020). "Given the opposing effects of SIRT1 in different brain regions, additional studies examined the effects of ICV injection of SRT2104 on CUS-induced depression-related behaviors." (PMID 30705425, 2020). "However, the exact neural network that mediates SIRT1 actions on depression remains unclear." (PMID 30705425, 2020). "Our results provide the first evidence that SIRT1, an NAD+-dependent class III histone deacetylase, in forebrain excitatory neurons exerts sexually dimorphic effects on depression-like behaviors." (PMID 30705425, 2020). "Sirtuin 1 (SIRT1), is a nicotinamide adenine dinucleotide (NAD+)-dependent protein deacetylase and a candidate gene for depression." (PMID 33228716, 2020). "Taken together, a potential molecular regulation of miR-124 on SIRT1 is revealed by our study and miR-124 suppression in PFC is a potential strategy to reduce depression-like behavior." (PMID 31431514, 2019). "Previous genomic studies in humans indicate that SIRT1, a nicotinamide adenine dinucleotide (NAD+)-dependent protein deacetylase, is involved in anxiety and depression, but the mechanisms are unclear." (PMID 30271963, 2018). "His study also demonstrated that HSYA activates SIRT1 and Nrf2 as well as inhibits p‐p65 expression in the hippocampus of CUMS rats, suggesting that HSYA may also impact depression by activating the SIRT1/Nrf2/NF‐kB pathway." (PMID 40059449, 2025). "Impaired expression of both SIRT1 and PGC-1α may exacerbate the decline in mitochondrial function, leading to metabolic disorders, which could potentially trigger depression." (PMID 40699781, 2025). "The findings indicated that the isolated mice displayed clear signs of anxiety and depression-like behaviors, along with increased levels of various cytokines (IL-1β, IL-6, and TNF-α) in the hippocampus and decreased levels of Sirt1, accompanied by elevated NF-κB p65 expression." (PMID 41317200, 2025). "Through the SIRT1/PGC-1α signaling pathway, this process increases the number and function of mitochondria, thereby improving mitochondrial energy metabolism and alleviating the occurrence of depression." (PMID 40699781, 2025). "Interestingly, we found that the therapeutic effect of paeoniflorin was changed by blocking the expression of SIRT1, which indicated that SIRT1 and NLRP3/GSDMD played a key role in the relief of depression by paeoniflorin." (PMID 39684254, 2024). "Therefore, the SIRT1-dependent PGC-1α/NRF1/TFAM signaling pathway, which mediates mitochondrial biogenesis, plays a significant role in the intervention of anxiety and depression-like behaviors." (PMID 39744519, 2024). "However, pharmacological activation or local overexpression of SIRT1 in the hippocampus or BNST can reverse chronic stress-induced anxiety- and depression-like behaviors." (PMID 39744519, 2024). "The expression of SIRT1 in the NAc and hippocampus CA1 showed a depression-promoting effect, but whether exercise affects the expression of SIRT1 in NAc remains to be answered." (PMID 37239191, 2023). "Altogether, these findings reveal that modulating the HO-1/MAPK, P13K/Akt, SIRT1- NLRP3, and Notch/HES-1-NF-κB signaling pathways might be the mechanism of AG in mitigating neuroinflammation, cognitive impairment, depression, and AD." (PMID 37920216, 2023). "All these findings suggest that upregulation of SIRT1 inhibits the levels of inflammatory factors such as GSK3β, TNF-α, and NF-κB to suppress the inflammatory response and exhibit anti-inflammatory effects, thereby improving depression-like behaviors." (PMID 37239191, 2023).
depression (continued). "According to the mechanisms of SIRT1 and exercise in improving depression, a speculation is that exercise activates the expression of SIRT1 to improve the HPA axis, inhibiting the inflammatory response and promoting neurogenesis, thereby improving depression." (PMID 37239191, 2023). "Overall, exercise can promote the expression of BDNF and CREB by increasing SIRT1 expression in the hippocampus, and moreover, it can activate the SIRT1/IGF-1/GAP-43 and SYN signaling pathways to increase the volume of SVZ and SGZ, improving neurogenesis, and eventually relieving depression." (PMID 37239191, 2023). "Therefore, suppression of SIRT1 expression can protect neuronal plasticity and maintain the 5-HT homeostasis via the NHLH2/MAO-A pathway, thereby improving depression-like behaviors." (PMID 37239191, 2023). "Therefore, it is inferred that exercise can inhibit miR-124 after upregulating SIRT1 expression in the hippocampus, and then upregulate GR to improve HPA axis function and realize anti-depression." (PMID 37239191, 2023). "Interestingly, Sirt1 is an NAD+ dependent histone deacetylase and mediates the levels of anxiety and depression." (PMID 35130906, 2022). "We found that lncRNA-84277 in CeA could function as a competing endogenous RNA (ceRNA) by sponging miR-128-3p to regulate SIRT1 expression and SNI-induced depression-like behaviors." (PMID 35959106, 2022). "Moreover, selectively inhibited Sirt1 and AMPK were able to compromise the therapeutic effect of PAP on depression." (PMID 35401226, 2022). "SIRT-1 levels are lower in bipolar depression than in euthymia, and TNF-α levels may be lower in depression than in mania." (PMID 34295268, 2021). "Although it is possible that other SIRTs, such as SIRT1 and SIRT2, might also regulate neurogenesis, aging, and even depression, we decided to focus only on SIRT3 in this study, given its central role in mitochondrial metabolism and oxidative protection." (PMID 35011652, 2021). "Furthermore, we found that the up- and downregulation of miR-155-5p also altered the expression of SIRT1, which was consistent with the previous literature that miR-155-5p could be used as a target gene to regulate SIRT1 and participate in the treatment of major depressive disorder." (PMID 34893074, 2021). "The findings indicated that the ATP played a vital role in the regulation of depression independent of SIRT1." (PMID 33228716, 2020). "SIRT1 and phosphoinositide 3-kinase (PI3K), for instance, are activated in both GC and depression." (PMID 31396300, 2019). "Since SIRT1 is involved in the regulatory system of MAO-A in the brain, miR-34c could be used as a therapeutic target for depression." (PMID 30271325, 2018). "Recent studies demonstrated that SIRT1 affects the levels of neurotransmitter by modulating the mono-amine oxidases MAO-A promoter and finally plays a beneficial role in the anxiety and depression." (PMID 27065808, 2016). "We noted a significant negative correlation between peripheral SIRT1 mRNA expression and the level of immobility in the FST, meaning that lower SIRT1 levels are associated with a more extensive depression-like phenotype in ESI-treated mice (r=0.65, P<0.001)." (PMID 26327687, 2015). "If this model was true, we would expect variations in SIRT1 levels to correlate significantly with depression-related measures in ESI-treated mice but not in animals in which a depression-like phenotype was induced by similar isolation stress during adulthood." (PMID 26327687, 2015). "Therefore, we speculated that TGGR might alleviate depression by downregulating AMPK and upregulating the expression of PGC-1α and SIRT1 genes." (PMID 39684318, 2024). "However, the effects of paeoniflorin on depression and the SIRT1-NF-kB-NLRP3 signaling pathway have not been studied." (PMID 39684254, 2024).
depression (continued). "In the present study, we found that maternal separation led to anxiety- and depression-like behaviors in offspring, the upregulation of the hippocampal levels of pro-inflammatory cytokines (IL-1β, IL-6, and TNF-α), and the inhibition of the Sirt1/NF-κB signaling pathway." (PMID 37273278, 2023). "In addition, this study noted that SIRT1 knock-out upregulated TNF-α expression, which reduced 5-HT concentration and simultaneously activated the activity of IDO, increasing the contents of KYN and QUIN and then inducing depression." (PMID 37239191, 2023). "Secondly, we only examined the changes in the expression of inflammatory factors and the Sirt1/NF-κB signaling pathway in hippocampal regions and did not evaluate the changes in these indicators in other anxiety- and depression-related brain regions, such as the amygdala." (PMID 37273278, 2023). "Therefore, based on the results obtained in this study, we hypothesized that S-ketamine mediated synaptic structure through SIRT1 and BDNF in depression." (PMID 35664490, 2022). "However, what has yet to be further elucidated is whether the anti-inflammatory effects contribute to the SIRT1 and SIRT2 modulators’ protection in the depression models and other mechanisms involved in symptoms or disorders." (PMID 33669121, 2021). "Therefore, in order to fully understand the role of SIRT1 and SIRT2 modulators, and potential treatment guidelines in the clinical setting, there needs to be consideration of the impact of sex in animal models of depression." (PMID 33669121, 2021). "In addition, we measured the peripheral mRNA expression of SIRT1 in 89 schizophrenia patients with depression and 108 without depression." (PMID 32849821, 2020). "Combination with the discrepant changes of SIRT1 in depression, we speculated that SIRT1 could not play a direct role in the pathogenesis of depression." (PMID 33228716, 2020). "However, the functional role of SIRT1 in glutamatergic neurons and its impact on depression-related behaviors have not previously been investigated." (PMID 30705425, 2020). "The absence of an effect of SIRT1 modulation on depression-like behavior in adults is consistent with this hypothesis." (PMID 26327687, 2015). "Therefore, we hypothesize that FOXO1-regulated microglia may potentially exacerbate brain damage and depression post-TBI while PI3K/Akt, TLR/NF-κB or AMPK/SIRT1 signaling pathways may interact with FOXO1 to regulate neutrophil activities in TBI requiring further investigation." (PMID 38556884, 2024). "Silent mating type information regulation 2 homolog 1 (SIRT1) is a protein in the Sirtuin family, and recent studies suggested that SIRT1 protein could affect monoamine transmitter levels in the brain by activating MAO-A transcription, thus the dysregulation of SIRT1 may be involved in depression." (PMID 30897781, 2019).
gastric cancer (117 papers, 2011 to 2026). A primary or metastatic malignant neoplasm involving the stomach. "In gastric cancer tissues, high expression of SIRT1 was closely associated with the degree of tumor differentiation, depth of invasion, and TNM stage (p < 0.05)." (PMID 41020376, 2025). "In rectal cancer, lower SIRT1 expression levels were observed to be significantly associated with unfavorable overall survival (OS) in gastric cancer (p = 0.027, HR = 0.41)." (PMID 41020376, 2025). "The high expression of SIRT1 and Beclin-1 (Atg6) is associated with shorter overall survival and reduced relapse-free survival in gastric cancer patients." (PMID 31492861, 2019). "The results suggest that in the progression of H. pylori-associated gastric cancer, CagA induces overexpression of miR-543, which subsequently targets SIRT1 to suppress autophagy." (PMID 31423013, 2019). "We therefore postulated that miR-543 expression is increased by CagA, targets SIRT1, and inhibits autophagy in H. pylori-associated gastric cancer." (PMID 31423013, 2019). "Dual-luciferase reporter assays revealed that miR-543 directly targeted SIRT1 and caused translational repression in gastric cancer cells." (PMID 31423013, 2019). "Collectively, the results suggested that miR-543 directly targeted SIRT1 and caused translational repression in gastric cancer cells." (PMID 31423013, 2019). "Studies of the molecular mechanisms responsible for gastric cancer progression highlight SIRT1 association with STAT3." (PMID 30761005, 2019). "Associations of SIRT1 expression with poor survival have also been found in patients with other gastrointestinal cancers, including liver, pancreatic and gastric cancers." (PMID 28977971, 2017). "In contrast, another study reported that SIRT1 expression is associated with poor prognosis but DBC1 expression is associated with favorable prognosis of gastric cancer patients." (PMID 25823848, 2015). "The expression of both DBC1 and SIRT1 is reported to be associated with a poor prognosis in gastric cancer." (PMID 25146318, 2014). "We investigated the correlation between SIRT1 expression and progression and prognosis of gastric cancers comparing with molecules linked to SIRT1 in order to better predict the efficacy of HDAC inhibitors in treating this disease." (PMID 25146318, 2014). "In conclusion, we found that high expression of SIRT1 was closely associated with progression and prognosis in gastric cancer patients." (PMID 25146318, 2014). "In this study, we investigated the expression of SIRT1 in gastric cancer patients and its association with clinicopathological factors and outcomes." (PMID 25146318, 2014). "We verified that miR-204 levels were down-regulated and significantly associated with the up-regulation of SIRT1 mRNA levels in gastric cancer specimens." (PMID 23768087, 2013). "Association between SIRT1 expression and clinicopathological data of patients with gastric cancer." (PMID 41020376, 2025). "Besides, contradicting associations between SIRT1 expression and survival outcomes were observed in two different cohorts of Korean gastric cancer patients." (PMID 28061480, 2017). "Sirt1 overexpression is associated with a poor prognosis in gastric cancer." (PMID 25815791, 2015). "Notably, we found that miR-204 down-regulation was significantly associated with up-regulation of SIRT1 mRNA levels in gastric cancer specimens." (PMID 23768087, 2013). "The expression of miR-204 and SIRT1 mRNA in 24 gastric cancer tissues and the matched normal tissues were evaluated using qRT-PCR to assess the role of miR-204 and its association with SIRT1 expression in gastric cancer tissues." (PMID 23768087, 2013). "It was found that in gastric cancer, higher SIRT1 expression levels were strongly linked to unfavorable overall survival (OS) in GC (p = 0.032, HR = 1.49)." (PMID 41020376, 2025). "However, the mechanism of SIRT1 up-regulation and its association with metastasis in gastric cancer remain unclear." (PMID 23768087, 2013).
gastric cancer (continued). "At the same time, it can regulate the expression of SIRT1 in cervical cancer and gastric cancer through the ceRNA mechanism." (PMID 41487470, 2026). "In this study, we observed a marked upregulation of SIRT1 expression in gastric cancer tissues, while a significant downregulation was evident in colon and rectal cancers compared with normal mucosal tissues." (PMID 41020376, 2025). "In gastric cancer peritoneal metastasis, hypoxia-induced autophagy degrades SIRT1, increasing HIF-1α acetylation and VEGFA signaling, enhancing adhesion and invasion." (PMID 41213956, 2025). "The plasma SIRT1 expression was (4.96 ± 2.59) ng/mL in 66 patients with gastric cancer, 43 of whom were male and 23 of whom were female, and the age range was 34–76 (58.91 ± 9.78) years." (PMID 41020376, 2025). "Specifically, overexpression of SIRT1 in gastric cancer correlated with tumor differentiation, infiltration depth, and TNM stage (p < 0.05)." (PMID 41020376, 2025). "Overexpression of SIRT1 in gastric cancer tissues was found to have a significant correlation with tumor differentiation, infiltration depth, and TNM stage (p < 0.05)." (PMID 41020376, 2025). "In contrast, SIRT1 activation inhibits cyclin D1 transcription and cell growth in gastric cancer, suggesting two aspects of SIRT1 activation in promoting or suppressing tumor growth." (PMID 39940750, 2025). "In our study, we found that the expression level of SIRT1 was higher in gastric cancer patients and lower in colon and rectal cancer patients." (PMID 41020376, 2025). "In gastric cancer, SIRT1-mediated deacetylation of ATG2B enhances autophagy and invasiveness, correlating with poor prognosis." (PMID 41213956, 2025). "In gastric cancer, SIRT1 deacetylates ATG2B, enhancing its RNF5-mediated ubiquitination and degradation, thereby suppressing autophagy and promoting tumor progression." (PMID 41213956, 2025). "The protein SIRT1 was mostly found in the nucleus, and its expression was considerably higher in gastric cancer cells compared to normal tissues (p < 0.0001)." (PMID 41020376, 2025). "The activation of USP14 determines the increased stability of the SIRT1 protein and is essential for the activation of fatty acid oxidation and the immunosuppressive phenotype in macrophages derived from gastric cancer." (PMID 39944823, 2025). "In cases of gastric cancer, there was a positive correlation between SIRT1 and CD4+ T cells (r = 0.166), CD8+ T cells (r = 0.295), macrophages (r = 0.285), and neutrophils (r = 0.218)." (PMID 41020376, 2025). "SIRT1 is also known to influence chemoresistance in a variety of malignancies, including ovarian, breast, and gastric cancers." (PMID 39403142, 2024). "MDM2-modulated Sirt6 upregulation and Sirt1 downregulation promoted gastric cancer cell death via increasing ROS accumulation." (PMID 38254877, 2024). "We showed that Sirt6 upregulates MDM2, which suppresses Sirt1 expression and induces ROS production, thereby promoting gastric cancer cell death." (PMID 38254877, 2024). "In this study, we examined the anti-tumorigenic effect of Sirt6 on inducing ROS-related gastric cancer cell death by suppressing Sirt1 expression." (PMID 38254877, 2024). "Among the seven mammalian sirtuin proteins, Sirt6 and Sirt1 seem to be key factors of gastric cancer cell death." (PMID 38254877, 2024). "Studies have shown that SIRT1 can accelerate the progression of gastric cancer by deacetylating β-catenin and promoting the activation of the Wnt signaling pathway." (PMID 39845948, 2024).